KRTCAP3 (keratinocyte associated protein 3)
Synonyms: KCP3
Tractability: Antibody: UniProt predicts a signal peptide or a membrane-spanning region. PROTAC: ubiquitination databases record sites on it.
Gene: Protein-coding gene on chromosome 2 (27,442,337 to 27,446,481, forward strand). Ensembl gene ENSG00000157992.
Subcellular location: Membrane
Subcellular location (Human Protein Atlas): Cytosol; Nucleoplasm
Gene Ontology:
Molecular function: protein binding
Cellular component: membrane
Genetic constraint (gnomAD): Loss-of-function variants: 17 observed, 18.49 expected, observed/expected ratio (o/e) 0.92, 90% interval 0.63 to 1.38. The synonymous counts are far from expectation, so gnomAD's model fits this gene poorly and the ratio says little. Missense variants: 327 observed, 290.91 expected, observed/expected ratio (o/e) 1.12, 90% interval 1.03 to 1.23. Synonymous variants: 166 observed, 132.54 expected, observed/expected ratio (o/e) 1.25, 90% interval 1.1 to 1.42.
Homologues: Orthologues: chimpanzee KRTCAP3 (99% identical), macaque KRTCAP3 (96% identical), pig KRTCAP3 (90% identical), dog KRTCAP3 (87% identical), mouse Krtcap3 (86% identical), rabbit KRTCAP3 (85% identical), rat Krtcap3 (81% identical), guinea pig KRTCAP3 (81% identical), tropical clawed frog krtcap3 (50% identical). Paralogues in human: TMEM54 (31% identical).
Diseases named in the same sentence as KRTCAP3 in open-access papers:
KRTCAP3 is named in the same sentence as 19 diseases in open-access papers, as found by Europe PMC text mining. Sharing a sentence is not in itself a finding about the gene and the disease. The quoted sentences say what the papers report.
Obesity (3 papers, 2018 to 2024). Accumulation of substantial excess body fat. "Future studies will seek to better understand these sex differences, the role of diet, and establish a mechanism for Krtcap3 in obesity." (PMID 36212147, 2022). "By being the first to confirm Krtcap3 as a novel obesity gene, however, this work sets the stage for future mechanistic studies." (PMID 36212147, 2022). "Another group also found that Krtcap3 is a potential pleiotropic gene for obesity, type 2 diabetes (T2D), and dyslipidemia in humans, indicating translational relevance." (PMID 36212147, 2022). "In the rat model, liver Krtcap3 expression was negatively correlated with fat mass, suggesting a protective role against obesity." (PMID 36212147, 2022). "Although little is known about the function of KRTCAP3, it affects obesity and insulin sensitivity." (PMID 38658550, 2024). "The differences we see in phenotype may be explained by Krtcap3 having a larger effect size in females relative to males, which is supported by literature on sex-specific obesity loci, where loci explain more variance in women than men." (PMID 36212147, 2022). "Beyond this knowledge, Krtcap3 has been poorly studied, in obesity and overall." (PMID 36212147, 2022).
Insulin resistance (2 papers, 2022 to 2023). Increased resistance towards insulin, that is, diminished effectiveness of insulin in reducing blood glucose levels. "Decreased expression of KRTCAP3 led to weight gain in female rats on a high-fat diet, while in male rats, it led to an increase in insulin resistance without weight gain." (PMID 37762215, 2023).
melanoma (2 papers, 2018 to 2023). A malignant, usually aggressive tumor composed of atypical, neoplastic melanocytes. "In the context of cancer, hypermethylated KRTCAP3 was identified in melanoma samples and melanoma cell lines compared to normal melanocytes, while no clear difference in mRNA expression was found." (PMID 37762215, 2023). "Moreover, genes showing hypermethylation in melanoma such as KRTCAP3, AGAP2, ZNF490, and TTC22 were newly recognized in the present study." (PMID 30719424, 2018). "Interestingly, while hypermethylation reduced KRTCAP3 mRNA expression in established melanoma cell lines, no significant downregulation was observed in fresh primary melanoma samples, PM2 and PM3, and melanocyte samples." (PMID 30719424, 2018).
Anxiety (1 paper, 2023). Intense feelings of nervousness, tension, or panic often arise in response to interpersonal stresses. "We found here that Krtcap3-KO rats were susceptible to the current stress paradigm, with corresponding increases in adiposity and anxiety-like behavior." (PMID 38323241, 2023). "Taken together, findings in the NSF, OFT, FST, and food intake under social isolation indicate that stress exposure leads to the expected increases in anxiety-like and depression-like behaviors when Krtcap3 expression is low." (PMID 38323241, 2023).
endometrial cancer (1 paper, 2020). Primary or metastatic malignant neoplasm involving the endometrium (mucous membrane that lines the endometrial cavity). "KRTCAP3 was reported to be overexpressed in gastric cancer and human keratinocytes, while KLHL14 participated in the development and metastasis of endometrial cancer." (PMID 32716025, 2020).
endometriosis (1 paper, 2025). The growth of functional endometrial tissue in anatomic sites outside the uterine body. "The role of “hubs” in these endometriosis-significant interactions was performed by proteins such as FNDC4 (participates in 9 pair interactions), NRBP1 and ZNF512 (7 pair interactions each), C2orf16, GPN1, and KRTCAP3 (6 pair interactions each)." (PMID 41373783, 2025).
gout (1 paper, 2024). A condition characterized by painful swelling of the joints, which is caused by deposition of urate crystals. "We validated a concordant direction of effect sizes of CTBP1, PPM1G, SEPT2, and KRTCAP3 for gout; SKIV2L for heart failure; and AAK1, MAPKAPK5-AS1, POLA2, RSG1, and WWP2 for hypertension." (PMID 38658550, 2024).
liver disease (1 paper, 2018). "SNPs in the region of EFNA1, DPM3 and KRTCAP3 have previously been associated with prostate cancer risk and γ-glutamyl transferase (GGT), an indicator of liver disease." (PMID 29659830, 2018).
mastocytosis (1 paper, 2023). A clonal myeloproliferative neoplasm characterized by the proliferation and accumulation of neoplastic mast cells in one or multiple organs or organ systems. "Furthermore, increased expression of genes encoding integral membrane components (GRM2 and KRTCAP3) was found in mastocytosis patients." (PMID 37762215, 2023). "Thus, the hypomethylation and increased expression of KRTCAP3, which we found in mastocytosis, could be potentially linked to a better prognosis; this requires further studies in the context of progression to the advanced forms of the disease." (PMID 37762215, 2023). "Significant differences in the expression of the selected genes were found for GRM2 (p = 0.013) and KRTCAP3 (p = 0.036) in mastocytosis patients compared to the heathy controls." (PMID 37762215, 2023). "The results of gene expression profiling indicate the increased expression of genes belonging to the integral component of the membrane in mastocytosis patients (GRM2 and KRTCAP3)." (PMID 37762215, 2023).
cancer (3 papers, 2022 to 2023). A tumor composed of atypical neoplastic, often pleomorphic cells that invade other tissues. "Little else is known about the underlying function of Krtcap3, with previous work showing a role in sheep wool production and some human cancers." (PMID 36212147, 2022). "The remaining genes in the hyperloss category are ECHDC3, KRTCAP3, LURAP1, and MAMDC4, none of which are known drivers in cancer." (PMID 37245006, 2023).
KRTCAP3 also shares sentences with these, for which no sentence is quoted: tumor (2 papers); depression (1); dyslipidemia (1); gastric cancer (1); heart failure (1); Hyperglycemia (1); Hypertension (1); prostate carcinoma (1); type 2 diabetes (1).